CDKN1A (cyclin dependent kinase inhibitor 1A)
Diseases named in the same sentence as CDKN1A in open-access papers (continued):
Sharing a sentence is not in itself a finding about the gene and the disease.
meningioma (3 papers, 2012 to 2023). A generally slow growing tumor attached to the dura mater. "Others have shown that CDKN1A is downregulated in less aggressive meningiomas, especially fibroblastic meningioma." (PMID 29662628, 2018). "Some studies have shown that levels of CDKN1A (p21) immunoexpression correlated with MIB-1 immunoexpression in meningioma and increased with increasing tumor grade." (PMID 29662628, 2018). "Regarding downstream gene cascades of Akt, apoptosis-induced genes including CASP9 (3.78-fold), CDKN1A (8.64-fold), AXIN2 (2.78-fold), APC2 (3.12-fold), and EP300 (5.35-fold) were detected with significant down-regulation in fibroblastic meningiomas." (PMID 23285163, 2012). "Irrespective of their conclusions it seems that CDKN1A has an important role in meningioma growth and proliferation." (PMID 29662628, 2018). "In our study, fibroblastic meningioma was detected with increasing expression of CCND1, CDK6, and E2F3, and decreasing expression of CDKs inhibitors including CDKN1A, CDKN2A, and CDKN2B, suggesting a role of cell cycle deregulation in the tumorigenesis of fibroblastic meningioma." (PMID 23285163, 2012).
metastatic disease (3 papers, 2022 to 2024). "Loss of the tumour suppressor genes RB1 (6p21) and CDKN1A (13q14) may explain enrichment of these genetic alterations in our cohort of metastatic tumours." (PMID 35231161, 2022). "Finally, to assess our findings in HGSOC patient population, we measured CDKN1A and VEGFA transcripts levels from primary and corresponding metastatic tumor tissues." (PMID 35884426, 2022).
osteoporosis (3 papers, 2015 to 2023). A condition of reduced bone mass, with decreased cortical thickness and a decrease in the number and size of the trabeculae of cancellous bone (but normal chemical composition), resulting in increased fracture incidence. "Furthermore, to explore the actual expression of genes on D6, we validated cdkn1a and several representative osteoporosis-associated genes by quantitative real-time polymerase chain reaction (qRT‒PCR) in the WT and DEX-treated zebrafish." (PMID 36599933, 2023). "To summarize, in this study, we provided new insights into the dynamic nature of osteoporosis and identified cdkn1a as an early-warning signal of osteoporosis onset." (PMID 36599933, 2023). "Overall, our findings confirmed the reliability of the DNB method and the key function of cdkn1a in osteoporosis." (PMID 36599933, 2023). "To explore the restorative effects of cdkn1a knockdown on the osteoporosis model, we performed cdkn1a knockdown on zebrafish at 6, 8, and 10 dpf while adding 10 μM DEX mix." (PMID 36599933, 2023). "To better illustrate the role of cdkn1a as an osteoporosis promotor, we performed bone mineralization and endogenous genetic tests on cdkn1a knockout and overexpression models." (PMID 36599933, 2023). "Others have reported that cdkn1a can resist osteoporosis by activating the Nrf2/HO-1 signaling pathway." (PMID 36599933, 2023). "However, little attention was previously paid to the function of cdkn1a in osteoporosis, which ranked third in our screening." (PMID 36599933, 2023). "To determine the early warning signs before osteoporosis, we used the dynamic network biomarker (DNB) approach to analyze time-series gene expression data in a zebrafish osteoporosis model, which revealed that cyclin-dependent kinase inhibitor 1 A (cdkn1a) is a core DNB." (PMID 36599933, 2023). "The cdkn1a knockout effect indeed confirmed the robustness of our findings about the role of cdkn1a and usefulness of the marker as the triggering event in the progression of osteoporosis." (PMID 36599933, 2023). "We proposed cdkn1a as an early-signaling indicator of the preosteoporosis state, against which therapies could be designed, thereby improving our understanding of the molecular pathogenesis of osteoporosis onset for early diagnosis and even mitigation." (PMID 36599933, 2023). "In the cdkn1a gain-of-function zebrafish model, osteoclast-related gene expression was upregulated, accompanied by mineral absorption, but osteoblast-related gene expression was not changed significantly, which demonstrated a relationship between age and the presence of drug-induced osteoporosis." (PMID 36599933, 2023). "In addition, differential expression analysis indicated that CDKN1A was remarkably upregulated in primary osteoporosis patients compared with healthy donors of both middle and old ages, suggesting the functional importance for osteoporosis." (PMID 36599933, 2023). "However, the role of cdkn1a in zebrafish osteoporosis initiation remains unclear." (PMID 36599933, 2023). "Therefore, FOSL1, RELA and CDKN1A may also be also involved in the pathogenesis of osteoporosis." (PMID 25815782, 2015). "In addition, we tested whether the effect of an osteoporosis inducer, such as DEX, could be reversed by cdkn1a knockout." (PMID 36599933, 2023).
Parkinson disease (3 papers, 2015 to 2025). A progressive degenerative disorder of the central nervous system characterized by loss of dopamine producing neurons in the substantia nigra and the presence of Lewy bodies in the substantia nigra and locus coeruleus. "In Parkinson’s disease patients, SATB1 (a CDKN1A inhibitor) levels are reduced in the substantia nigra, while CDKN2A, MMP3, IL-6, IL-1α, and CXCL8 levels are elevated, indicating an increased aging burden." (PMID 39963130, 2025). "In addition, the pathway of huntington disease and parkinson disease highly expressed in CD82 and CDKN1A." (PMID 39966875, 2025).
preeclampsia (3 papers, 2015 to 2021). Preeclampsia is a hypertensive disorder of pregnancy that is characterized by new-onset hypertension with proteinuria presenting after 20 weeks of gestation, and depending on mild or severe forms may initially present with severe headache, visual disturbances, and hyperreflexia. "Neither of the loci has been previously shown to function in association with CRP, although mRNA expression of inflammation-related genes in leukocytes might be able to upregulate CDKN-1A, at least in preeclampsia." (PMID 25951190, 2015). "In relation to the cell cycle and proliferation, evidence shows that CCND1 is decreased in placentas from IUGR and preeclampsia complicated with IUGR, while CDKN1A is increased in IUGR placentas." (PMID 28380025, 2017).
prostate adenocarcinoma (3 papers, 2019 to 2025).
prostate tumor (3 papers, 2012 to 2016). "Moreover, 3 genes STAT1, ERBB3, P21 (CDKN1A) were found to be associated with ‘prostatic neoplasms regulation of progression through cell cycle’ and 1 gene STAT1 is associated with ‘prostatic neoplasms inflammatory response’." (PMID 22870216, 2012). "Tumors with overexpressed miR-190a had reduced expression of AR, YB-1 and Ki-67, and increased CDKN1A, suggesting that overexpression of miR-190a inhibited prostate tumor growth in vivo." (PMID 26314494, 2015).
renal fibrosis (3 papers, 2022 to 2025). A final common manifestation of a wide variety of chronic kidney diseases characterized by glomerulosclerosis and tubulointerstitial fibrosis. "In contrast, the X-inactive specific transcript lncRNA XIST is markedly upregulated in DN and sponges the anti-fibrotic miR-93-5p, thereby de-repressing Cyclin-Dependent Kinase Inhibitor 1A (CDKN1A) and exacerbating renal fibrosis." (PMID 41300780, 2025). "No toxicity or alteration in levels of renal fibrosis was seen in uninjured control kidneys treated with Loc14 versus vehicle, and inhibition did not affect senescent cell number, as measured by Cdkn1a or Cdkn2a via qPCR or P21CIP1 expression on immunofluorescence." (PMID 36509292, 2022).
small cell lung carcinoma (3 papers, 2021 to 2022). Small cell lung cancer (SCLC) is a highly aggressive malignant neoplasm, accounting for 10-15% of lung cancer cases, characterized byrapid growth, and early metastasis. "The study showed that CDKN1A upregulation induced by miR-93-5p CDKN1A could block the TGF-β and thus increase the therapeutic effects of chemotherapy on small cell lung cancer cells." (PMID 35340229, 2022). "CircRNA cESRP1 was sensitized to small cell lung cancer (SCLC) cells upon chemotherapy (i.e., doxorubicin, CDDP and etoposide) by sponging miR-93-5p, and upregulating expression of the miR-93-5p downstream target, Smad7/p21(CDKN1A)." (PMID 34295810, 2021).
T-cell acute lymphoblastic leukemia (3 papers, 2021 to 2024). Acute lymphoblastic leukemia of T-cell origin. "CDKN1A is also a target of several miRNAs involved in T-cell acute lymphoblastic leukemia, suggesting that total mRNA expression of CDKN1A is regulated by mechanisms other than direct nascent mRNA synthesis inhibition." (PMID 34685458, 2021).
alcoholic liver diseases (2 papers, 2025). A disorder caused by damage to the liver parenchyma due to alcohol consumption. "Additionally, the expression of CDKN1A and CDKN2A, as well as the presence of TAF, has been observed in non-alcoholic fatty liver disease, and TAF has also been reported in alcoholic liver disease." (PMID 39963130, 2025).
amyotrophic lateral sclerosis (2 papers, 2015 to 2022). Amyotrophic lateral sclerosis (ALS) is a neurodegenerative disease characterized by progressive muscular paralysis reflecting degeneration of motor neurons in the primary motor cortex, corticospinal tracts, brainstem and spinal cord. "While in other types of skeletal muscle atrophy, such as Duchenne muscular dystrophy, amyotrophic lateral sclerosis, aging and critical illness, CDKN1A mRNA is one of the most highly induced skeletal muscle mRNAs." (PMID 35847900, 2022). "Furthermore, CDKN1A and GADD45A are also related to other muscular disorders such as amyotrophic lateral sclerosis." (PMID 25567521, 2015).
atopic dermatitis (2 papers, 2021 to 2024). "In addition, phenotype scanning has shown that CDKN1A is associated with trunk fat-free mass, trunk predicted mass, and triglycerides, while total cholesterol is associated with atopic dermatitis." (PMID 39512814, 2024).
Atrophy (2 papers, 2015 to 2021). Any weakening or degeneration, especially through lack of use. "GADD45A and CDKN1A have previously been identified in several conditions associated with muscle atrophy." (PMID 25567521, 2015). "HDAC4 also regulates cell division, cell cycle, apoptotic process, and cell differentiation via CDKN1A and SIK1, involving in denervation-induced muscle atrophy." (PMID 34276308, 2021). "In the starvation induced atrophy model, ATF4 can increase the expression levels of downstream CDKN1A and GADD45 α." (PMID 34276308, 2021). "Taken together, HDAC4 inhibition can alleviate denervation-induced muscle atrophy by reducing MYOG expression, and HDAC4 is also directly related to CDKN1A and SIK1 in skeletal muscle, which suggests that HDAC4 inhibitors may be a potential drug for the treatment of neurogenic muscle atrophy." (PMID 34276308, 2021).
breast adenocarcinoma (2 papers, 2014 to 2022). "It is worth noticing, that CDKN1A additionally connects the panels “steroids” and “mammary adenocarcinoma”." (PMID 24955840, 2014). "Interestingly, CDKN1A was computed to be an important nexus gene between the panels “insulin resistance” - “ROS” - “mammary adenocarcinoma”, with an induced expression at day 21 and day 28 (2.3-fold, p<0.00001)." (PMID 24955840, 2014). "It is worth noticing, that CDKN1A also links the panels “steroids” and “mammary adenocarcinoma”." (PMID 24955840, 2014). "Our in silico analysis identified the cyclin-dependent kinase inhibitor 1a (CDKN1A, also known as p21) as a gene of future interest, as it links the gene panels of “ROS”, “insulin resistance” and “mammary adenocarcinoma”." (PMID 24955840, 2014).
Cachexia (2 papers, 2021). Severe weight loss, wasting of muscle, loss of appetite, and general debility related to a chronic disease. "Cdkn1a (p21) was recently identified as a gene most robustly upregulated in cachectic muscle when integrating transcriptome datasets across five different cachexia models." (PMID 35008253, 2021). "Among the upregulated genes, Il6ra, Cdkn1a, Csf2rb2, and Akt1, and among the downregulated genes, Col1a1 and other collagen-related genes were involved in multiple pathways, suggesting their key function in cachexia." (PMID 34175899, 2021).
chromophobe renal cell carcinoma (2 papers, 2020). Chromophobe renal cell carcinoma is a rare subtype of renal cell carcinoma, originating from the intercalating cells of the collecting ducts and macroscopically manifesting as a well-circumscribed, highly lobulated, solid tumor that is usually diagnosed at an early stage. "We also identified CDKN1A alterations in the metastatic groups, and loss of CDKN1A had been proved to be an unfavorable predictor of prognosis in chromophobe renal cell carcinoma patients." (PMID 33062672, 2020).
chronic hepatitis (2 papers, 2009 to 2023). An active inflammatory process affecting the liver for more than six months. "Ablation of Cdkn1a in hepatocyte-specific NEMO-deficient mice, which develop chronic hepatitis, leads to spontaneous HCC." (PMID 36765862, 2023).
chronic kidney disease (2 papers, 2021 to 2025). Impairment of the renal function secondary to chronic kidney damage persisting for three or more months. "Interestingly, another study also suggested that knocking out the CDKN1A gene can clearly improve chronic kidney disease." (PMID 34338139, 2021).
diffuse large B-cell lymphoma (2 papers, 2013 to 2017). "Chromatin immunoprecipitation (ChIP) experiments confirmed that EZH2 binds to the CDKN1A promoter in primary human GC B cells and diffuse large B cell lymphoma (DLBCL) cell lines, with concordant enrichment of its H3K27me3 repressive mark." (PMID 29026085, 2017).
dilated cardiomyopathy (2 papers, 2021 to 2024). Cardiomyopathy which is characterized by dilation and contractile dysfunction of the left and right ventricles. "In our study, genes regulated by AP-1, namely CDKN1A, SAT1, and ZFP36, were found to be downregulated in DCM (dilated cardiomyopathy) myocardium compared to normal myocardium." (PMID 38886541, 2024). "Therefore, the present study also for the first time reported ferroptosis related gene CDKN1A and pyroptosis related gene PRKACA may be involved in the development and progression of dilated cardiomyopathy." (PMID 34970603, 2021).
Duchenne muscular dystrophy (2 papers, 2021 to 2022). Duchenne muscular dystrophy (DMD) is a neuromuscular disease characterized by rapidly progressive muscle weakness and wasting due to degeneration of skeletal, smooth and cardiac muscle. "Studies have shown that the expression of CDKN1A in the muscle of children with Duchenne muscular dystrophy is increased, and it is also up-regulated in the muscle of the elderly." (PMID 34276308, 2021).
Dystonia (2 papers, 2014 to 2017). An abnormally increased muscular tone that causes fixed abnormal postures. "CDKN1A directly interacts with the dystonia-associated protein CIZ1." (PMID 24936516, 2014).
EBV infection (2 papers, 2021 to 2024). "BID and CDKN1A are both involved in the pathway of EBV infection that has been previously discussed." (PMID 33785040, 2021). "One was the Epstein-Barr virus infection pathway (q-value=0.025), represented by four upregulated genes (CDKN1A, NFKB2, RELB, and PDIA3) and two downregulated genes (BID and HLA-A)." (PMID 33785040, 2021).
gynecologic cancers (2 papers, 2016 to 2018).
Hepatitis (2 papers, 2008 to 2023). Inflammation of the liver. "Proteins that uniquely distinguish HCC patients with low AFP from patients with hepatitis include IL1RN, IFNG, CDKN1A, RETN, CXCL14, and FGF2." (PMID 19578489, 2008). "Importantly, we also identified 8 proteins that significantly differentiate HCC patients with ‘normal’ levels of AFP (< 20 ng/ml) from hepatitis patients (p < 0.05) (IL1RN, IFNG, CDKN1A, RETN, CXCL14, CTNNB, FGF2, and SELL)." (PMID 19578489, 2008).
influenza (2 papers, 2015). An acute viral infection of the respiratory tract, occurring in isolated cases, in epidemics, or in pandemics; it is caused by serologically different strains of viruses (influenzaviruses) designated A, B, and C, has a 3-day incubation period, and usually lasts for 3 to 10 days. "In addition to IFI27 and PI3 that have the largest expression difference between influenza and HRV, CDKN1A and CDKN1C, which are essential genes involved in cell cycle control, appeared to be differentially expressed specifically in influenza virus infection." (PMID 26070066, 2015). "Several other pro-apoptotic genes including TNFRSF12A, DDIT3, and CDKN1A were upregulated in SUS animals, indicating that they may also contribute to apoptotic events during influenza infection in swine." (PMID 26393920, 2015).
injury (2 papers, 2023 to 2025). Damage inflicted on the body as the direct or indirect result of an external force, with or without disruption of structural continuity. "By analysis of the published data from the ischemic AKI model developed with unilateral renal ischemia–reperfusion injury (GSE192883), the relative gene expression of Nfe2l2, Plk2, and Cdkn1a was upregulated." (PMID 35842499, 2023).
ischemic stroke (2 papers, 2022 to 2024). A stroke disorder caused by obstruction of blood flow to the brain, due to thrombotic (local blood clot formation) or embolic (due to a blood clot or other material traveling from another site) event. "To observe the changes in the four biomarkers CDKN1A, GPX4, PRDX1, and PRDX6 in patients with ischemic stroke, we measured their expression of these four biomarkers in peripheral blood using RT-PCR." (PMID 38360841, 2024). "The results showed that CDKN1A, PRDX1, and PRDX6 expression levels were significantly increased, which was consistent with our study, suggesting that CDKN1A, PRDX1, and PRDX6 may be involved in the occurrence and development of ischemic stroke." (PMID 38360841, 2024).
keratoconus (2 papers, 2024). A degenerative, structural disorder of the eye, characterized by a cone-shaped protrusion of the cornea. "The findings of this study indicate that the expression of CDKN1A is decreased in keratoconus compared to control corneas, suggesting impairment in the processes of DNA replication and DNA damage repair in keratoconus." (PMID 38830963, 2024). "The expression of CCR2, CDKN1A, HSPA5, MAPK8IP1, PPP1R15A, and VEGFA in individuals with keratoconus was significantly different from that in control subjects." (PMID 38830963, 2024).
lung neoplasm (2 papers, 2011 to 2021). A benign or malignant, primary or metastatic neoplasm involving the lungs. "Overall from previous and current tumor analyses using different dosing regimens, carcinogens, and strains of mice, a panel of common transcripts (e.g. Arg1, Areg, Ereg, Ccr2, Cdkn1a, Gja1, Ptgis, Spp1) may provide a useful tool for early diagnosis of lung neoplasm." (PMID 22039513, 2011).